NUCB2 (nucleobindin 2)
Diseases named in the same sentence as NUCB2 in open-access papers (continued):
Sharing a sentence is not in itself a finding about the gene and the disease.
renal carcinoma (6 papers, 2020 to 2024). A carcinoma arising from the epithelium of the renal parenchyma or the renal pelvis. "In a NUCB-2-knockout renal cancer cell line SK-RC-52, the expression levels of molecules associated with epithelial-mesenchymal transition (EMT), including E-cadherin, β-catenin, Slug and Twist, were affected by NUCB-2 suppression." (PMID 37635259, 2023). "In renal cancer cells, miR-149 is sponged by circular RNA circ_00150, which resulted in the NUCB2 increase." (PMID 34361082, 2021). "NUCB2/NESF-1 knockout in the SK-RC-52 renal cancer cell line affected EMT-related proteins such as E-cadherin, β-catenin, Slug, and Twist." (PMID 34361082, 2021). "To conclude, NUCB-2/NESF-1 was identified as a valid marker associated with tumorigenesis and progression of renal cancer." (PMID 34361082, 2021). "Additionally, NUCB2/NESF-1 knockdown in the 786-O renal cancer cell line inhibited cell proliferation by arresting the cell cycle at the S phase." (PMID 34361082, 2021). "On the other hand, NUCB2/NESF-1 knockdown in renal cancer cells increased cell apoptosis." (PMID 34361082, 2021). "It was demonstrated that NUCB2/NESF1 intensified proliferation, invasion, and migration processes in colon, breast, endometrial, papillary thyroid, bladder, and renal cancer cells." (PMID 36012443, 2022). "Mechanistically, it has been shown that NUCB2/nesfatin-1 improved the migration, invasion, and EMT characteristics of colon and renal cancer cells through stimulation of the AMPK/TOC1/ZEB1 pathway." (PMID 36585713, 2022). "Recent studies have indicated that NUCB2/NESF-1 enhanced migration, invasion, and EMT properties of colon and renal cancer cells through AMK/TOC1/ZEB1 pathway activation." (PMID 34361082, 2021). "Moreover, reduced tumor volume and growth rate were observed in NUCB2/NESF-1-knockdown renal cancer cells in the mice model compared to that in the negative control group." (PMID 34361082, 2021).
renal cell carcinoma (6 papers, 2017 to 2025). "Interestingly, the association of EMT promotion by Nucb2 with the AMPK/mTORC1/ZEB1 pathways has also been reported for renal cell carcinoma cells." (PMID 34073612, 2021). "As in the renal cell carcinoma, only one study which included 188 patients showed that NUCB2 expression was an indicator for worse prognosis in patients with ccRCC." (PMID 27806328, 2017). "Surprisingly, this pro-apoptotic effect of Nucb2/nesfatin-1 is contradictory to the effect previously observed for colon and renal cell cancers, where Nucb2/nesfatin-1, through the AMPK/mTOR signaling pathways, contributed to the enhanced aggressiveness and invasiveness of these tumors." (PMID 34073612, 2021). "A high expression of Nucb2, in comparison to adjacent non-cancerous cells, was found in breast, prostate, colon, endometrial, papillary thyroid, and renal cell carcinomas." (PMID 34073612, 2021).
adrenocortical carcinoma (5 papers, 2017 to 2025). "In adrenocortical carcinoma, elevated NUCB2/nesfatin-1 levels induced the expression of the pro-apoptotic protein Bax21." (PMID 39309426, 2024).
clear cell renal cell carcinoma (5 papers, 2017 to 2025). "Nesfatin-1 precursor, NUCB2, was also assessed in terms of prediction of renal clear cell carcinoma (ccRCC), the most frequent histological variant of RCC." (PMID 39480586, 2025). "Several studies have shown that NUCB2/nesfatin-1 is expressed in various malignancies, including gastric, breast, prostate, and clear cell renal cell cancers." (PMID 40964608, 2025). "This study aimed to investigate the prognostic significance of NUCB2 in clear cell renal cell carcinoma." (PMID 27806328, 2017).
colorectal cancer (5 papers, 2020 to 2025). A primary or metastatic malignant neoplasm that affects the colon or rectum. "To conclude, NUCB2/NESF-1 is suggested to be associated with aggressive progression in colorectal cancer." (PMID 34361082, 2021). "In colorectal cancer, up-regulation of NUCB2 was reported to associate with metastasis and aggravate the carcinoma progression." (PMID 32226311, 2020).
Hypoglycemia (4 papers, 2014 to 2025). A decreased concentration of glucose in the blood. "Available studies in mammals have shown that a subpopulation of NUCB2/nesfatin-1-expressing neurons is activated in the rat brain in response to hypoglycemia, and that nesfatin-1 modulates the excitability of glucosensing neurons in the rat brain." (PMID 30210451, 2018).
lung adenocarcinoma (4 papers, 2020 to 2025). A carcinoma that arises from the lung and is characterized by the presence of malignant glandular epithelial cells. "A study on lung adenocarcinoma demonstrated that Lnc-FTX is upregulated in tumor tissues and accelerates malignant characteristics of Lung adenocarcinoma by activating the miR-335-5p/NUCB2 pathway." (PMID 40084261, 2025).
lymph node metastasis (4 papers, 2013 to 2024). "In 150 non-invasive (pT1) and invasive (pT2/pT3/pT4) GC, high NUCB2 IHC scores were significantly associated with unfavorable prognostic factors including deep invasion, lymph-vascular tumor invasion, lymph node metastasis, and advanced clinical stage." (PMID 38760405, 2024). "Our results indicated that the high expression of NUCB2 in PCa was associated with lymph node metastasis, preoperative PSA, Gleason score, and angiolymphatic invasion." (PMID 23958433, 2013). "Furthermore, it was found that a higher NUCB2/NESF-1 level was observed in tumors with estrogen receptor expression and was positively associated with lymph node metastasis." (PMID 34361082, 2021). "Furthermore, it was also shown that NUCB2/NESF-1 protein expression was significantly associated with seminal vesicle invasion, higher levels of preoperative PSA, positive lymph node metastasis, positive angiolymphatic invasion, biochemical recurrence, and higher Gleason scores." (PMID 34361082, 2021). "The high level of Nucb2 mRNA expression was related to a higher Gleason score, a higher level of preoperative prostate-specific antigen (PSA), positive lymph node metastasis, and angiolymphatic invasion." (PMID 34073612, 2021). "The results also indicated a positive correlation between NUCB2/NESF-1 expression and lymph node metastasis and the TNM stage." (PMID 34361082, 2021). "Second, this is the first report to describe the significance of NUCB2 to preoperative PSA, gleason score, angiolymphatic invasion, lymph node metastasis of PCa patients." (PMID 23958433, 2013). "Patients with lymph node metastasis showed a higher expression of NUCB2/NESF-1 compared to those without lymph node metastasis (49.5%, vs. 36.6%, p = 0.043)." (PMID 34361082, 2021).
thyroid cancer (4 papers, 2021 to 2025). "The study showed that knockdown of NUCB2/NESF-1 in thyroid cancer cells decreased invasion-related proteins (MMP-2 and MMP-9)." (PMID 34361082, 2021). "Moreover, proliferation-related proteins (Ki-67 and PCNA) were decreased in NUCB2/NESF-1 shRNA-transfected thyroid cancer cells compared to the control." (PMID 34361082, 2021). "Additionally, decreased invasion ability of NUCB2/NESF-1-silenced TPC-I and KI thyroid cancer cell lines was observed compared to the control." (PMID 34361082, 2021).
anorexia nervosa (3 papers, 2015 to 2018). A disorder most often seen in adolescent females characterized by a refusal to maintain a minimally normal body weight, an intense fear of gaining weight, a disturbance in body image, and, in postmenarcheal females, the development of amenorrhea. "Normal weight patients displayed about twofold higher NUCB2/nesfatin-1 levels compared to matched anorexia nervosa patients (0.393 ± 0.368 vs. 0.156 ± 0.09 ng/ml)." (PMID 26162003, 2015). "We analyzed circulating NUCB2/nesfatin-1 levels in 64 female inpatients diagnosed with anorexia nervosa (body mass index, BMI; mean±SD, 14.7±2.3 kg/m2)." (PMID 26162003, 2015). "The only study conducted in subjects with anorexia nervosa reported lower NUCB2/nesfatin-1 levels compared to healthy controls." (PMID 26162003, 2015). "NUCB2/nesfatin-1 is an anorexigenic hormone with elevated levels in obese and decreased levels in anorexia nervosa (AN) patients." (PMID 26162003, 2015). "Correlation of NUCB2/nesfatin-1 plasma levels with demographic and psychometric parameters of the anorexia nervosa study population (n = 64)." (PMID 26162003, 2015). "Nesfatin-1 is a well-established anorexigenic hormone in rodents and NUCB2/nesfatin-1 blood levels were reported to be reduced in patients with restricting-type anorexia nervosa suggesting an implication of this peptide in the onset, course or maintenance of the disease." (PMID 26162003, 2015). "In the present study, we did not detect an association of circulating NUCB2/nesfatin-1 with the total score of EDI-2 or its subscales in subjects with anorexia nervosa." (PMID 26162003, 2015). "Normal weight patients also displayed a tendency towards a significant difference with markedly higher NUCB2/nesfatin-1 levels compared to anorexic patients which may be due to the influence of the higher body weight compared to anorexia nervosa." (PMID 26162003, 2015). "In addition, we exploratively did not observe an association of NUCB2/nesfatin-1 with eating disorder symptoms as measured by the EDI-2 making NUCB2/nesfatin-1 unlikely to be directly involved in eating disorder pathology in anorexia nervosa." (PMID 26162003, 2015).
anxiety disorder (3 papers, 2015 to 2024). A category of psychiatric disorders which are characterized by anxious feelings or fear often accompanied by physical symptoms associated with anxiety. "Interestingly, male patients with general anxiety disorders displayed decreased nesfatin-1 levels pointing towards a possible sex-specific regulation of NUCB2/nesfatin-1." (PMID 26162003, 2015).
eating disorder (3 papers, 2015 to 2023). A broad group of psychological disorders with abnormal eating behaviors leading to physiological effects from overeating or insufficient food intake. "Moreover, until now studies are lacking that investigate the relationship between NUCB2/nesfatin-1 and behaviors, cognitions or attitudes in eating disorders." (PMID 26162003, 2015).
injury (3 papers, 2018 to 2022). Damage inflicted on the body as the direct or indirect result of an external force, with or without disruption of structural continuity. "NUCB2 is linked to inflammation and coagulopathies, and is correlated with mortality following brain injury." (PMID 30037347, 2018). "Because exogenously applied NUCB2/nesfatin-1 is reported to suppress inflammation of post traumatic brain injury, increase of NUCB2/nesfatin-1 which was found in this study is likely to reflect the anti-inflammatory response rather than result of neuroinflammation itself." (PMID 33318307, 2020).
multiple sclerosis (3 papers, 2020 to 2023). A progressive autoimmune disorder affecting the central nervous system resulting in demyelination. "Here, we aimed to investigate the involvement of NUCB2/nesfatin-1 in a representative neuroinflammatory disease, multiple sclerosis (MS)." (PMID 33318307, 2020).
nasopharyngeal carcinoma (3 papers, 2021 to 2025). A carcinoma arising from the nasopharyngeal epithelium. "The association of NUCB-2/Nesfatin-1 with nasopharyngeal carcinoma (NPC) remains unclear." (PMID 37635259, 2023). "In nasopharyngeal carcinoma cell lines (5-8 F, 6-10B, CNE1, CNE2 and NP69), western blotting, MTT, EdU and other techniques were performed to investigate the role of NUCB-2 in nasopharyngeal carcinoma." (PMID 37635259, 2023). "NUCB2 was revealed to be a target gene of miR-30a-5p in nasopharyngeal carcinoma (NPC)." (PMID 34361082, 2021). "This study revealed that NUCB-2 could enhance proliferation of NPC cells and NUCB-2/nesfatin-1 has the potential to be a serological marker to aid early diagnosis of nasopharyngeal carcinoma." (PMID 37635259, 2023). "Moreover, the results of ROC analysis suggest that NUCB-2 detection is of great significance for the early diagnosis of NPC; combination of serological nefastin-1 with EB virus antibodies is effective to improve the detection rate of early nasopharyngeal carcinoma." (PMID 37635259, 2023).
type 1 diabetes (3 papers, 2017 to 2025). "Both NUCB2 mRNA expression and nesfatin-1 immunoreactivity were found to be decreased in the pancreatic islets of mice with type 1 diabetes, while increased in the islets of diet-induced obese mice with T2DM." (PMID 28533821, 2017).
acute lymphoblastic leukemia (2 papers, 2021 to 2024). Leukemia with an acute onset, characterized by the presence of lymphoblasts in the bone marrow and the peripheral blood. "Nucleobindin 2 (NUCB2) was first described in 1994 in KM3 acute lymphoblastic leukemia cell line as a DNA binding/EF-hand/acidic-amino acid-rich protein." (PMID 34361082, 2021). "Human nucleobindin 2 (NUCB2), is primarily found in 1994 in acute lymphoblastic leukemia cells." (PMID 39309426, 2024).
breast tumors (2 papers, 2022 to 2023). "NUCB2 expression in breast tumors was weakly positive correlated with the patient’s age (r = 0.1029, p = 0.0327) Moreover, the expression of the protein was higher in elderly patients (age ≥ 66, p = 0.0136) (data not shown)." (PMID 36012443, 2022).
generalized anxiety disorder (2 papers, 2015 to 2025). An anxiety disorder characterized by excessive and difficult-to-control worry about a number of life situations. "Interestingly, one recent human study detected decreased NUCB2/nesfatin-1 plasma levels in male patients with the diagnosis of a generalized anxiety disorder compared to healthy controls which could point towards a sex-specific regulation of NUCB2/nesfatin-1." (PMID 26162003, 2015).
hepatocellular carcinoma (2 papers, 2024 to 2025). A malignant tumor that arises from hepatocytes. "Except that, we also assessed the effects of NUCB2 on mouse hepatoma cell proliferation and metastasis." (PMID 39309426, 2024).
ischemia (2 papers, 2019 to 2024). A hypoperfusion of the BLOOD through an organ or tissue caused by a PATHOLOGIC CONSTRICTION or obstruction of its BLOOD VESSELS, or an absence of BLOOD CIRCULATION. "NUCB2 significantly reduced the Bax and GFAP protein levels in the CA1 area after ischemia (P<0.05)." (PMID 32284834, 2019).
necrotizing enterocolitis (2 papers, 2022). Necrotizing enterocolitis (NEC) is a devastating disease that affects mostly the intestine of premature infants. "NUCB2/nesfatin-1 is widely expressed in the mammalian gastrointestinal tract, and it has been shown to reduce inflammation and oxidative stress during ulceritis, necrotizing enterocolitis, and acute mesenteric ischemia." (PMID 36499229, 2022).
non-small cell lung carcinoma (2 papers, 2025). A group of at least three distinct histological types of lung cancer, including non-small cell squamous cell carcinoma, adenocarcinoma, and large cell carcinoma. "The expression of nesfatin-1 protein and NUCB2 mRNA was detected in the immortalized normal human bronchial cell line BEAS-2B and the non-small-cell lung cancer cell line H1299." (PMID 40964608, 2025). "In the present study, we demonstrated that NUCB2/nesfatin-1 affects the proliferation and migration of human lung cells, specifically the normal bronchial epithelial cell line BEAS-2B, but not the non-small cell lung cancer cell line H1299." (PMID 40964608, 2025).
papillary thyroid cancer (2 papers, 2021 to 2022). "A recent study have indicated that NUCB2/nesfatin‐1 was expressed in both the nucleus and cytoplasm of papillary thyroid cancer cells." (PMID 36065769, 2022). "The immunohistochemistry evaluation of the presence of NUCB2/NESF-1 in 155 cases of papillary thyroid cancer revealed nucleus and cytoplasmic expression." (PMID 34361082, 2021).
preeclampsia (2 papers, 2021 to 2025). Preeclampsia is a hypertensive disorder of pregnancy that is characterized by new-onset hypertension with proteinuria presenting after 20 weeks of gestation, and depending on mild or severe forms may initially present with severe headache, visual disturbances, and hyperreflexia. "In preeclampsia, there is a report of decreased circulating NUCB2/nesfatin-1 protein levels, as well as of increased nesfatin-1 peptide concentration in circulation." (PMID 34681721, 2021).
pyometra (2 papers, 2024 to 2025). "The results showed significantly higher nesfatin-1 encoding gene, nucleobindin-2 mRNA (Nucb2) and nesfatin-1 protein expression in overweight females and those suffering from CEH or pyometra compared to healthy animals." (PMID 39455994, 2024). "Our previous study showed significantly higher Nucb2 expression and nesfatin-1 protein production in overweight bitches and those suffering from CEH or pyometra compared to healthy animals." (PMID 40144052, 2025).
relapsing-remitting MS (2 papers, 2020 to 2022). "When comparing the levels of NUCB2/nesfatin-1 in control subjects, patients with primary progressive MS and relapsing remitting MS, average NUCB2/nesfatin-1 level was significantly higher in CSF of relapsing remitting MS patients." (PMID 33318307, 2020).
B cell lymphomas (1 paper, 2009). "Finally, the gene coding for nucleobindin 2 (Nucb2) implicated in B cell lymphomas was also up-regulated." (PMID 19799787, 2009).
benign prostatic hyperplasia (1 paper, 2013). A non-cancerous nodular enlargement of the prostate gland. "Therefore, the NUCB2 protein expression was measured in PCa tissues and benign prostatic hyperplasia (BPH) tissues by and immunohistochemistry." (PMID 24422979, 2013). "Through immunohistochemistry, NUCB2 protein expression was evaluated in 60 benign prostatic hyperplasia (BPH) specimens and 180 PCa specimens." (PMID 24422979, 2013).
brain tumors (1 paper, 2025). "Among the upregulated secreted proteins in LvM16, nucleobindin 2 (NUCB2) and human deleted in malignant brain tumors 1 (DMBT1) ranked at the top." (PMID 40796724, 2025).
Cerebral ischemia (1 paper, 2019). Restriction of arterial blood supply to the brain associated with insufficient oxygenation to support the metabolic requirements of the tissue. "However, the role of NUCB2 or so-called nesfatin-1 in cerebral ischemia-reperfusion has been poorly investigated." (PMID 32284834, 2019). "However, the therapeutic effects of NUCB2 have not been well investigated in cerebral ischemia." (PMID 32284834, 2019).
gastric tumours (1 paper, 2002). "Moreover, comparison of mRNA levels between cancerous and adjacent non-cancerous tissues by RT–PCR showed that the expression of NUCB2 is downregulated in 50% of gastric tumours." (PMID 12087473, 2002). "An unusual DNA polymorphism – a three-nucleotide deletion was found in NUCB2 cDNA but its mRNA level was consistently decreased in gastric tumours compared with that in the adjacent non-cancerous tissues." (PMID 12087473, 2002).
glioma (1 paper, 2023). A benign or malignant brain and spinal cord tumor that arises from glial cells (astrocytes, oligodendrocytes, ependymal cells). "Kaplan–Meier analysis revealed that higher NUCB2 expression was significantly associated with worse survival outcomes in glioma patients." (PMID 37830634, 2023). "In our review, similar to other cancers, high NUCB2 expression correlates with higher pathological grading of glioma, and patients with high NUCB2 expression have a worse prognosis." (PMID 37830634, 2023).
hepatic (1 paper, 2025). "However, we found that in NUCB2-KO rats fed an HFD, the inhibitory effect of intestinal glucose or lipid infusion on HGP disappeared, indicating that under HFD conditions, NUCB2-KO impairs intestinal nutrient-sensing mechanisms and exacerbated hepatic IR." (PMID 39562740, 2025).
hypogonadism (1 paper, 2024). A disorder characterized by decreased function of the gonads. "Also, combining PTU, Se, and a miRNA targeting NUCB2 could ascertain the precise role of nesfatin‐1 as a mediator of selenium's protection against hypothyroid‐induced hypogonadism." (PMID 38268116, 2024).